CD2 (CD2 molecule)
Diseases named in the same sentence as CD2 in open-access papers (continued):
Sharing a sentence is not in itself a finding about the gene and the disease.
bronchitis (1 paper, 2018). An acute or chronic inflammatory process affecting the bronchi. "Infant CD2 suffered from pharyngitis; CD3 suffered from an upper respiratory tract infection; CD5 suffered from otitis; CD6 and CD8 suffered from an upper respiratory tract infection and also from otitis, and control C5 suffered from bronchitis." (PMID 29458413, 2018).
Castleman disease (1 paper, 2024). Castleman disease (CD) is a benign lymphoproliferative disorder that may present as a localized or multicentric form. "Supporting this hypothesis, physiological interactions between FcγRIIIa/CD16 and the co-stimulatory receptor CD2 were shown to be necessary to induce direct NK cytotoxicity but not ADCC in a patient with EBV-driven Castleman’s disease homozygous for H in position 66 (rs10127939)." (PMID 39051331, 2024).
chloroma (1 paper, 2006). "Fine-needle aspiration with flow cytometry revealed expression of HLA-DR and CD13 but a lack of CD2, CD3, CD4, CD8, suggesting the diagnosis of chloroma." (PMID 16623775, 2006).
co-infection (1 paper, 2021). "Similarly, co-infection induced the highest proportion of IFN-γ+ CD2+ γδ T cells in the Vac group (mean 0.22%), and IL-17+ CD2+ γδ T cells in the Ctrl group (mean 0.30%)." (PMID 34858411, 2021).
E. coli infection (1 paper, 2025). "E. coli infection increased the proportion of RFP+ cells that co-express Ki67 in mice of Lyz2+ and Gli1+ cell lineages, but not in mice of Cd2+ and S100a4+ cell lineages." (PMID 39748675, 2025).
epilepsy (1 paper, 2015). A brain disorder characterized by episodes of abnormally increased neuronal discharge resulting in transient episodes of sensory or motor neurological dysfunction, or psychic dysfunction. "Additionally, cD2 KO mice, which lack neurons born before KA treatment and display proliferation of progenitors at barely detectable levels after KA treatment, do develop epilepsy." (PMID 26020770, 2015). "To evaluate the impact of diminished neurogenesis on epileptogenesis and early epilepsy, we performed video-EEG monitoring of wt and cD2 KO mice for 16 days following SE." (PMID 26020770, 2015). "The significant reduction in adult neurogenesis did not prevent the development of epilepsy following KA-induced SE in cD2 KO mice." (PMID 26020770, 2015). "The difference in seizure frequency between cD2 KO and wt mice with diagnosed epilepsy was not statistically significant." (PMID 26020770, 2015). "One limitation of this study is that cD2 KO mice are not yet fully characterized in terms of aberrant network excitability or other pathologies that could influence epilepsy development." (PMID 26020770, 2015). "Our study using cD2 KO mice, which display markedly limited adult brain neurogenesis and in which proliferation of neural progenitors in the subgranular layer is negligible after KA-induced SE, indicates that neurogenesis is not required for SE-induced epileptogenesis and early epilepsy." (PMID 26020770, 2015).
glomerulonephritis (1 paper, 2021). A renal disorder characterized by damage in the glomeruli. "Interestingly, NK cells harvested from the spleens of anti-CD2 antibody-coated NPs treated mice had equivalent protective effects on the lupus-like glomerulonephritis as the anti-CD2 antibody-coated NPs loaded with IL-2." (PMID 34211471, 2021).
gout (1 paper, 2020). A condition characterized by painful swelling of the joints, which is caused by deposition of urate crystals. "Another two intergenic loci from normal type gout, rs146978188 of CD2-PTGFRN and rs548944057 of SLC28A3-NTRK2, were detected for the first time to have an association with gout." (PMID 32238385, 2020). "Three significant loci were found from normal type gout: rs548944057 of SLC28A3-NTRK2 (pmeta=2.91×10–8; OR=4.04), rs4148155 of ABCG2 (pmeta=3.64×10–8; OR=2.34) and rs146978188 of CD2-PTGFRN (pmeta=4.93×10–8; OR=6.31)." (PMID 32238385, 2020). "Of these, two loci from all gout types, rs76499759 of PIBF1 and rs9926388 of ACSM2B, and another two intergenic loci from normal type gout, rs146978188 of CD2-PTGFRN and rs548944057 of SLC28A3-NTRK2, were detected as novel loci." (PMID 32238385, 2020).
helminth infection (1 paper, 2021). "We used a CD2/IL-13 dual fluorescent reporter mouse for in vivo imaging of ILC2s and Th2 T cells in real time following a type 2 priming helminth infection or egg injection." (PMID 34484215, 2021).
Hernia (1 paper, 2021). "Among these, nine genes (CD2, GPT2, MOXD1, ENSSSCG00000031037, ENSSSCG00000032582, ENSSSCG00000036224, ENSSSCG00000036983, ENSSSCG00000037009 and ENSSSCG00000039111) had different expression profiles when comparing both types of hernia." (PMID 33513662, 2021).
Hypercholesterolemia (1 paper, 2013). An increased concentration of cholesterol in the blood. "The network in the MCA with largest number of up-regulated focus genes affected by hypertension plus hypercholesterolemia showed many molecules related to ERK 1/2, interferon alpha, IL12, SYK, CD2, CD4, and CD244." (PMID 23874591, 2013).
Hypoalbuminemia (1 paper, 2021). The concentration of albumin in the blood circulation is below the lower limit of normal. "Previous studies reported that these factors increased the risk of APL thrombosis, including male, high score performance status (PS), high white blood cell count and platelet count, low fibrinogen levels, hypoalbuminemia, PML/RARa fusion gene variant, CD2/CD15 and FLT3-ITD positive." (PMID 34130694, 2021).
invasive breast carcinoma (1 paper, 2021). A carcinoma that infiltrates the breast parenchyma. "For example, in invasive breast cancer, CD2 was an immune-related prognostic biomarker regulating the tumor microenvironment." (PMID 34408984, 2021).
liver fibrosis (1 paper, 2022). "To further elucidate the potential role of mTORC1 and mTORC2 in regulating γδ T cells function, we reconstituted Raptor-f/f-CD2-cre (RapKO) and Rictor-f/f-CD2-cre (RicKO) Vγ4 cells into TCRδ-/- mice respectively and then induced liver fibrosis." (PMID 35361750, 2022).
lobomycosis (1 paper, 2019). A chronic, fungal, subcutaneous infection endemic in rural regions in South America and Central America. "In addition, the proportion of CD4+ cells over the sum of CD2+ T lymphocytes and CD19+ B lymphocytes in “normal” dolphins was also 30% in a field study to quantify the immune changes in bottlenose dolphins with lobomycosis." (PMID 31481952, 2019).
lung adenocarcinoma (1 paper, 2022). A carcinoma that arises from the lung and is characterized by the presence of malignant glandular epithelial cells. "As to their prognostic values, seven genes could not predict the clinical outcome in NSCLC and lung squamous cell carcinoma (LUSC), while CD2 and HLA-DRA were associated with the improved prognosis in lung adenocarcinoma (LUAD)." (PMID 35794593, 2022).
lymphangioma (1 paper, 2024). A benign lesion composed of dilated lymphatic channels. "Lymphangiomas exhibit characteristic features such as chylous fluid and positive CD2–40 staining." (PMID 39391203, 2024).
lymphoproliferative disorder (1 paper, 2012). "Inserting a truncated TGFβRII under a CD2 promoter/enhancer in mice results in a CD8 T cell lymphoproliferative disorder with small lymphocyte infiltration." (PMID 23145171, 2012).
mast cell disease (1 paper, 2023). "While normally mast cells do not express CD2, CD25 and CD35, these antigens become expressed in clonal mast cell disease." (PMID 36694141, 2023).
myasthenia gravis (1 paper, 2020). Myasthenia gravis (MG) is a rare, clinically heterogeneous, autoimmune disorder of the neuromuscular junction characterized by fatigable weakness of voluntary muscles. "Eight associations (five variants) were not previously reported to our knowledge, including associations near IRF1/IL5 for myasthenia gravis, near TNFSF11 for RF− JIA, and near CD2/CD28 for EGPA." (PMID 33239102, 2020).
NK-cell leukemias (1 paper, 2004). "In the rare CD3- cases the cells are TCR-, CD2+, CD16+ and CD56+ representing, therefore, true NK-cell proliferations corresponding to the aggressive NK-cell leukemias or to the – usually benign – chronic NK-lymphocytosis." (PMID 15575964, 2004).
non-small cell lung carcinoma (1 paper, 2022). A group of at least three distinct histological types of lung cancer, including non-small cell squamous cell carcinoma, adenocarcinoma, and large cell carcinoma. "Among them, CD2, which is associated with malignancy in non-small cell lung cancer, shows stem cell characteristics." (PMID 35602471, 2022).
oral diseases (1 paper, 2025). "Thus, the nitrate-reducing capacity of CD2 may provide an additional mechanism for preventing acidification in the oral cavity, potentially helping to prevent oral diseases such as tooth decay." (PMID 40361594, 2025).
Oral ulcer (1 paper, 2020). Erosion of the mucous mebrane of the mouth with local excavation of the surface, resulting from the sloughing of inflammatory necrotic tissue. "The efficacy of lozenges containing L. brevis CD2 was also tested in the treatment of oral ulcers in Behcet’s syndrome patients, and a significant decrease in the number of oral ulcers after 1 and 2 weeks of therapy was observed." (PMID 32182651, 2020).
ovarian tumors (1 paper, 2024). "Interestingly, we have previously reported CD2 and COL5A2 in a single gene signature for immune subtyping of desert, excluded, and inflamed ovarian tumors, suggesting that underlying biological mechanisms behind immune TME formation can be at least in part shared among tumors in different organs." (PMID 38397409, 2024).
pancreatic ductal adenocarcinoma (1 paper, 2025). An infiltrating adenocarcinoma that arises from the epithelial cells of the pancreas. "Using the ART-TIME approach, we identify a AhR-ARNT-mediated co-signaling mechanism between PD-1 and CD2 as a driver in immune evasion of pancreatic ductal adenocarcinoma." (PMID 41372132, 2025).
panniculitis (1 paper, 2025). Inflammation of the subcutaneous adipose tissue. "Due to its nonspecific presentation and histological overlap with panniculitis, early diagnosis requires a high index of suspicion, prompt biopsy of nodular lesions, and immunophenotyping using markers such as CD2, CD3, CD8, granzyme B, and TIA-1." (PMID 40709991, 2025).
polycystic kidneys (1 paper, 2026). "Subsequent research using gene profiling of human polycystic kidneys has shown that genes associated with immune responses—such as complement 1s, IgG Fc receptor I, leukocyte common antigen, and CD2—were up-regulated in polycystic kidneys." (PMID 41431718, 2026).
preeclampsia (1 paper, 2024). Preeclampsia is a hypertensive disorder of pregnancy that is characterized by new-onset hypertension with proteinuria presenting after 20 weeks of gestation, and depending on mild or severe forms may initially present with severe headache, visual disturbances, and hyperreflexia. "Notably, the cell surface receptor CD2, which mediates nanotube formation and augments cytotoxicity, is a target of both IRF2 and IRF7 and was found to be upregulated in both preeclampsia and missed abortion." (PMID 39090334, 2024).
prostate carcinoma (1 paper, 2021). A carcinoma that arises from epithelial cells of the prostate gland. "This study aims to determine if the differential transcriptomic profiles of CD14+ and CD2+ cell populations are associated with features of adverse pathology in early stage, clinically localized prostate cancer." (PMID 34685549, 2021).
Seizure (1 paper, 2015). A seizure is an intermittent abnormality of nervous system physiology characterized by a transient occurrence of signs and/or symptoms due to abnormal excessive or synchronous neuronal activity in the brain. "Seizures were observed in 9 out of 12 cD2 KO mice and in 11 out of 15 wt mice (p>0.05, chi-square test)." (PMID 26020770, 2015).
squamous cell carcinoma of the (1 paper, 2019). "An identical treatment with the strain L. brevis CD2 has been used in two studies with squamous cell carcinoma of the head and neck patients undergoing radiotherapy." (PMID 31581434, 2019).
status epilepticus (1 paper, 2015). Status epilepticus is defined as a continuous seizure lasting more than 30 min, or two or more seizures without full recovery of consciousness between any of them. "First, we examined whether status epilepticus (SE) evoked by an intra-amygdala injection of KA induces cell proliferation in cD2 KO mice." (PMID 26020770, 2015).
T-cell neoplasm (1 paper, 2019). "Coexpression of CD2, CD4, CD7, and CD30 by the mast cells particularly in skin lesions may provoke misinterpretation as a cutaneous T-cell neoplasm." (PMID 31772790, 2019).
T-lymphoblastic lymphoma (1 paper, 2006). The most frequent type of lymphoblastic lymphoma. "The T-lymphoblastic lymphomas showed variable positivity of CD3, CD2 and CD10 markers." (PMID 17069647, 2006).
tumor (184 papers, 1996 to 2026). "By regulating CD2-associated signaling pathways, the immune system’s ability to recognize and eliminate tumor cells can be enhanced, offering new perspectives and potential strategies for BC treatment." (PMID 40496857, 2025). "Expanding our investigation, TISIDB database analysis revealed that across various tumor types, higher expression of CD2 was associated with a prolonged overall survival period and a reduced risk of mortality." (PMID 40615696, 2025). "In vivo studies showed that CD2‐deficient CTLs promoted tumor growth and brain metastasis while affecting metabolic reprogramming by altering key enzyme expressions in pyrimidine biosynthesis and arginine metabolism pathways." (PMID 40859981, 2025). "Compared to the BLCA tumour-adjacent normal tissues, tumour expression of transcripts encoding CD2, KLRK1, and NCR2 were higher." (PMID 39877370, 2024). "Immunohistochemical staining of the tumor cells showed positivity for CD2, CD3, CD4, CD5, CD25 and CD45 and partial loss of CD7." (PMID 36975591, 2023). "In vitro studies have shown that the deficiency of CD58 limits the recognition of tumor cells by T/NK cells, leading to immune evasion in a CD2/CD58‐dependent manner." (PMID 37904707, 2023). "One group has recently reported that the loss of the adhesion/costimulatory molecule CD58 (the ligand of CD2) at the surface of tumor cells from large B-cell lymphoma patients is associated with CD19 CAR T-cell failure." (PMID 36189315, 2022). "The transfer of MDSCs from Tff2-null mice resulted in a marked (10-fold) stimulation of tumour growth in CD2–Tff2 mice, converting the tumour-resistant CD2–Tff2 mice into a tumour susceptible phenotype." (PMID 26841680, 2016). "Through global transcriptome analysis, immune-related functions were found to be key regulators in the spleen associated with tumor progression as a function of age with CD2, CD3ε, CCL19, and CCL5 being the key molecules involved." (PMID 26497558, 2015). "Moreover, CD2 deficiency disturbs the urea cycle and pyrimidine biosynthesis, contributing to metabolic reprogramming that accelerates tumor progression and brain metastasis." (PMID 40859981, 2025). "Emerging evidence suggests that low CD2 expression may be associated with CTL exhaustion; however, whether CD2 regulates the metabolic crosstalk between CTLs and tumor cells remains unknown." (PMID 40859981, 2025). "Next, to assess whether Nrf2 expression affects the anti-tumor T cell response, we used Nrf2-deficient (Nrf2−/−) and Nrf2-transgenic (Tg) mice, in which Nrf2 was overexpressed under the control of the human CD2 (hCD2) promoter." (PMID 39169624, 2024). "Tumor growth and production of ascites were inhibited in Cbx3/HP1γ-deficient mice compared to controls or mice ectopically expressing Cbx3/HP1γ driven by the human T-cell-restricted Cd2 promoter (Cbx3/HP1γTg)." (PMID 34721405, 2021). "A decrease in the ZP magnitudes of CaP coatings deposited at 200–250 V was strongly associated with elevated hTERT expression in tumor-derived Jurkat T cells preliminarily activated with anti-CD2/CD3/CD28 antibodies and then contacted in vitro with CaP-coated samples for 14 days." (PMID 34279263, 2021). "Based on our data, a decrease in the ZP magnitudes of CaP coatings deposited at 200–250 V was strongly associated with elevated hTERT expression in tumor-derived Jurkat T cells preliminarily activated with anti-CD2/CD3/CD28 antibodies and then contacted in vitro with CaP-coated samples for 14 days." (PMID 34279263, 2021). "In addition, CD2 expression is associated with a variety of tumor-infiltrating immune cells (TIC)." (PMID 35602471, 2022). "In vitro studies demonstrated that T/NK-mediated cytotoxicity could be restored by re-expression of wild-type CD58, suggesting the deficiency of CD58 restrains the recognition of tumor cells by T/NK cells and evades immune surveillance in a CD2/CD58-dependent manner." (PMID 34193136, 2021).